KIAA0408 (KIAA0408)
Tractability: PROTAC: ubiquitination databases record sites on it.
Gene: Protein-coding gene on chromosome 6 (127,438,406 to 127,459,393, reverse strand). Ensembl gene ENSG00000189367.
Subcellular location (Human Protein Atlas): Nucleoplasm; Cytosol
Gene Ontology:
Molecular function: protein binding
Genetic constraint (gnomAD): Loss-of-function variants: 54 observed, 68.48 expected, observed/expected ratio (o/e) 0.79, 90% interval 0.63 to 0.99. The upper end of that interval is the gene's LOEUF score, 0.99, which puts it in group 4 of 6, group 1 being the genes least tolerant of losing a copy. Missense variants: 787 observed, 873.57 expected, observed/expected ratio (o/e) 0.9, 90% interval 0.85 to 0.96. Synonymous variants: 304 observed, 298.08 expected, observed/expected ratio (o/e) 1.02, 90% interval 0.93 to 1.12.
Homologues: Orthologues: chimpanzee KIAA0408 (99% identical), macaque KIAA0408 (94% identical), rabbit KIAA0408 (72% identical), pig KIAA0408 (71% identical), guinea pig KIAA0408 (62% identical), rat Kiaa0408L (56% identical), mouse 9330159F19Rik (55% identical), dog KIAA0408 (54% identical), tropical clawed frog KIAA0408 (30% identical).
Diseases named in the same sentence as KIAA0408 in open-access papers:
KIAA0408 is named in the same sentence as 4 diseases in open-access papers, as found by Europe PMC text mining. Sharing a sentence is not in itself a finding about the gene and the disease.
KIAA0408 shares sentences with these, for which no sentence is quoted: cancer (1 paper); colorectal adenocarcinoma (1); endometrioid carcinoma (1); tumor (1).